CXCR4 (C-X-C motif chemokine receptor 4)
Diseases named in the same sentence as CXCR4 in open-access papers (continued):
Sharing a sentence is not in itself a finding about the gene and the disease.
atherosclerosis (93 papers, 2007 to 2025). A disease characterized by the build-up of fatty material and calcium deposition in the arterial wall resulting in partial or complete occlusion of the arterial lumen. "The MIF/CXCR4 axis is relevant in atherosclerosis, as it has been associated with atherogenic activities of not only monocytes and T cells, but also neutrophils, platelets, and B cells." (PMID 40055309, 2025). "A previous study showed that blocking the CXCL12/CXCR4 chemokine receptor axis in mice can accelerate the process of atherosclerosis by causing an increase in the number of neutrophils in peripheral blood and plaques." (PMID 39759498, 2024). "We also elucidated a cluster of chemokine signaling regulation via microRNAs involving CXCL12 and CXCR4 (miR-126-5p/-3p, miR-146a-5p/-3p and miR-494-5p)—factors closely associated with atherosclerosis development and progression." (PMID 39337512, 2024). "This was also confirmed in a cohort of 50 patients suffering with atherosclerosis, in which it was demonstrated that the expression of CXCR4 is associated with high plasma levels of IgM anti malondialdehyde-LDL." (PMID 39095816, 2024). "Exemplarily, ApoE−/−mice repopulated with CXCR4-deficient bone marrow displayed reduced lesions in injury-driven atherosclerosis but exacerbated lesion formation in lipid-driven atherosclerosis." (PMID 35055054, 2022). "For a clearer picture of the association between EC CXCL12/CXCR4 and atherosclerosis, five different models of CXCL12-knockout were created, and the lesion area, macrophage content and collagen content were studied." (PMID 34494495, 2021). "CXCR4 expression in leukocytes is closely associated with the vulnerability of atherosclerosis plaque." (PMID 34552562, 2021). "CXCR4 deficiency also switches VSMCs from a contractile to a secretory phenotype (macrophage-like), favouring atherosclerosis." (PMID 34494495, 2021). "The expression of CXCR4 is also significantly upregulated under hypoxic conditions within atherosclerosis-associated cells." (PMID 31004184, 2019). "CXCL12 silencing resulted in a significant 42% reduction in adventitial lymph vessel density, underpinning the causal role that CXCR4/CXCL12 plays in atherosclerosis associated lymph vessel expansion." (PMID 28349940, 2017). "On the other hand, SDF-1/CXCR4 biological axis is associated with bone marrow-derived endothelial progenitor cells during the development of atherosclerosis." (PMID 26074989, 2015). "In a murine model of atherosclerosis the inhibition of the CXCR4-CXCL12 axis by AMD or transplantation of CXCR4 deficient bone marrow led to an increased number of circulating leukocytes (predominantly neutrophils) correlating with atherosclerotic lesions." (PMID 25152735, 2014). "An interesting observation was the significant reduction in CXCR4 expression in all the monocyte subsets—except for the CD14dCD16n subset—in the offART group, given that lower CXCR4 monocyte expression has been associated with subclinical atherosclerosis." (PMID 40362169, 2025). "Moreover, B cell-specific CXCR4 (C-X-C chemokine receptor type 4) deficiency, which resulted in reduced IgM levels in plasma, led to increased atherosclerosis in female mice." (PMID 35497984, 2022). "VSMCs deficient in CXCR4 exhibit a synthetic phenotype unable to maintain normal vascular reactivity and contractile responses which is connected to the development of atherosclerosis, demonstrating a potential atheroprotective effect of SMC-expressed CXCR4 (pathway 4)." (PMID 34501271, 2021). "However, until now there have been no studies directly investigating the causal cell-type-specific effects of CXCL12/CXCR4 in relation to atherosclerosis." (PMID 26257740, 2015). "Yet, the authors still claim that HIV infection of VSMCs through CXCR4 may be one reason why HIV patients are more susceptible to develop atherosclerosis." (PMID 24966838, 2014).
atherosclerosis (continued). "Chronic CXCR4 inhibition induces neutrophilia and increases the number of neutrophils in plaques, both of which are linked to apoptosis and a pro-inflammatory phenotype, suggesting that neutrophils may have pro-inflammatory roles in atherosclerosis." (PMID 36204316, 2022). "Interaction between C-X-C motif chemokine ligand 14 (CXCL14) and CXCR4 was found to promote monocyte and platelet migration, and it is involved in thrombus formation, whereas CXCR4 deficient in platelets interrupts the interaction, offering a novel therapeutic strategy for atherosclerosis treatment." (PMID 34445123, 2021). "In addition, the association of CXCR4 with atherosclerosis progression suggest that SDF1/CXCR4 signaling could be a possible atherosclerotic target." (PMID 34062730, 2021). "Two studies have identified CXCR4 as a critical regulator of B1 cell migration to the bone marrow, as CXCR4 deficiency resulted in decreased B1 cells in the bone marrow, reduced IgM levels, and elevated atherosclerosis in B-cell-specific CXCR4-deficient female Apoe−/− mice." (PMID 33572939, 2021). "In particular, ACKR3’s role in regulating CXCL12 bioavailability and modulating CXCR4-mediated chemotaxis positions it as an intriguing target to fine-tune B-cell activity in atherosclerosis." (PMID 40986007, 2025). "Another study showed that blocking TLR2/CXCR4 can significantly delay or perhaps even reverse atherosclerosis induced by Chlamydia pneumoniae infection." (PMID 40535169, 2025). "In this study, EGFR, VEGFA, HSP90AA1, SRC, HIF1A, CXCR4 and IGF1R were identified as key hub targets, which linked anthocyanins with atherosclerosis." (PMID 40478326, 2025). "While its role in these processes is clearer, the significance of CXCR4 in native atherosclerosis remains uncertain." (PMID 40143163, 2025). "CXCR4 has also been advocated to play a crucial role in atherosclerosis by mobilizing and recruiting progenitor and inflammatory cells." (PMID 39776816, 2025). "MIF binds to the chemokines CXCR2 and CXCR4, recruits leukocytes, and accelerates the process of atherosclerosis." (PMID 38625586, 2024). "The knockdown of CXCR4 alleviates the degree of CHD by promoting macrophage autophagy through the PI3K/AKT/mTOR pathway to reduce atherosclerosis." (PMID 39590363, 2024). "In a murine model of atherosclerosis, B-1a cells migrated from the peritoneal cavity to the BM in a CXCR4-dependent manner, where they secreted natural IgM against oxidation-specific epitopes." (PMID 39095816, 2024). "Vascular CXCR4 limits atherosclerosis by maintaining arterial integrity, preserving endothelial barrier function, and cell-specific enhancement of CXCR4 in vascular cells or B cells was able to therapeutically reduce atherosclerosis in mice." (PMID 38892201, 2024). "This conclusion is supported by the increase in atherosclerosis in both the arterial endothelial cell- and smooth muscle-specific deletion of CXCR4 in mice." (PMID 37894988, 2023). "Conversely, disruption of this signaling pathway by genetic deletion of vascular CXCR4 increases endothelial permeability and is permissive for the augmented recruitment of inflammatory cells, potentially driving the progression of atherosclerosis." (PMID 35055054, 2022). "Although extensive investigations have explored the role of CXCR4 expression in atherosclerosis, the basis of its metabolism is still incompletely understood." (PMID 35888127, 2022). "In contrast, a functional CXCR4 blockade exacerbates the progression of atherosclerosis, and the cell-specific deletion of CXCR4 in arterial endothelial cells or smooth muscle cells accelerates the progression of atherosclerosis in apoe−/− mice." (PMID 36670934, 2022). "These lines of evidence suggest that the role of CXCL12 and CXCR4 in atherosclerosis is still under debate." (PMID 36670934, 2022).
atherosclerosis (continued). "As vascular CXCL12 and CXCR4 were shown to significantly contribute to atherosclerosis, the aim of this study was to decipher the role of arterial ACKR3 in atherosclerosis, which is an important missing link in this chemokine-axis." (PMID 35674847, 2022). "Based upon our observations, we further confirmed the anti-atherogenic effect of bromelain by using PET/CT imaging with [68Ga]-APD, which has been designed as a PET tracer of CXCR4 for the imaging of atherosclerosis." (PMID 36670934, 2022). "In our opinion, the results we obtained indicate the important role of the CXCL12/CXCR4/CXCR7 axis in the development of atherosclerosis." (PMID 36077592, 2022). "Li and colleagues proposed CXCR4 as an interesting theranostic target for atherosclerosis since CXCR4-directed endoradiotherapy with 177Lu-/90Y-pentixather for hematologic malignancies showed an anti-inflammatory effect on atherosclerotic plaques." (PMID 33669804, 2021). "It has been demonstrated that disruption of neutrophil senescence, apoptosis, and systematic removal by blocking CXCR4 leads to aggravation of atherosclerosis, as there is increased adhesion and migration." (PMID 34494495, 2021). "Platelets express some functional chemokine receptors such as CCR1, 3, 4, and CXCR4, which are involved in infection, hemostasis, inflammation, and even in the development of atherosclerosis." (PMID 34425822, 2021). "The modulatory and regulatory functional spectrum of CXCL12/CXCR4/ACKR3 axis in atherosclerosis spans from proatherogenic, prothrombotic and proinflammatory to atheroprotective, plaque stabilizer and dyslipidemia rectifier." (PMID 34494495, 2021). "The C-X-C motif chemokine receptor 4 (CXCR4) is expressed on the surface of various cell types involved in atherosclerosis, including macrophages and T-cells." (PMID 34685553, 2021). "The CXCL12/CXCR4/ACKR3 axis performs distinct functions in the pathophysiology of atherosclerosis, ranging from atheroprotective to proatherogenic functions across various cell types, through its receptors CXCR4 and ACKR3." (PMID 34494495, 2021). "Some studies have reported that the expression of CXCR4 on macrophages was upregulated by pro-atherosclerotic factors, whereas other studies found a possible protective role of the CXCR4 in experimental atherosclerosis." (PMID 34062730, 2021). "Showing the predominant effect of CXCL12/CXCR4/ACKR3 axis in different cells involved in atherosclerosis." (PMID 34494495, 2021). "In the context of atherosclerosis, CXCR4-targeted imaging of vulnerable plaques via [68Ga]Pentixafor PET has already found its way into clinical application (see Section 3.2)." (PMID 34885030, 2021). "Matrix metalloproteinases (MMPs) are related to atherosclerosis progression through the SDF1/CXCR4 axis promoting macrophages recruitment within the vascular wall." (PMID 34062730, 2021). "The CXCL12-CXCR4 axis was also studied in the context of atherosclerosis with a focus on CXCR4 using diet-induced atherosclerosis mouse models." (PMID 33503867, 2021). "Based on these findings, we suspected that CXCR4 plays a significant role in chronic inflammatory disease treatment and prevention, such as atherosclerosis." (PMID 34067297, 2021). "CXCL12 is a member of the chemokine family exerting a myriad role in atherosclerosis through its classical CXCR4 and atypical ACKR3 (CXCR7) receptors." (PMID 34494495, 2021). "Previous studies suggested that the activation of CXCR4 in neutrophils mediates the formation of NETosis during chronic inflammation, such as in atherosclerosis and ischemic brain injury." (PMID 34948374, 2021). "In a rabbit model of atherosclerosis, it was shown that macrophage-rich plaques overexpress CXCR4 which can be imaged PET with 68Ga-pentixafor." (PMID 33669804, 2021). "In contrast to their findings regarding EC-specific CXCL12, EC-specific CXCR4 was shown to limit atherosclerosis by supporting endothelial barrier function." (PMID 33503867, 2021).
atherosclerosis (continued). "More exploration of CCL4 and CXCR4 secreted by PAT would enhance the understanding of the pathophysiological mechanism of atherosclerosis and facilitate its utilization as a biomarker and intervention target for atherosclerosis." (PMID 34552562, 2021). "As one of the most important receptors for stromal cell-derived factor 1, CXCR4 has been known to play a central role in angiogenesis, endothelial function, and atherosclerosis." (PMID 35174166, 2021). "To examine the therapeutic capacity of the CXCR4 mimic, we employed an established in vivo mouse model of early atherosclerosis, in which lesions develop in aortic root and arch over a 4–5-week time course of HFD44." (PMID 33239628, 2020). "Macrophage migration-inhibitory factor (MIF) is an atypical chemokine that promotes atherosclerosis through CXC-motif chemokine receptor-4 (CXCR4)." (PMID 33239628, 2020). "The relevance of the cell-specific contribution of CXCL12 and its receptor CXCR4 in the progression of atherosclerosis has been extensively proven, thus further linking the miR-126 duplex to atherosclerosis development." (PMID 32733281, 2020). "Nevertheless, systematic analyses of the exact functional expression of CXCR4 during atherosclerosis progression are required in order to offer robust cellular validation of CXCR4 as a specific marker of atherosclerosis." (PMID 31004184, 2019). "We also observed upregulated expression of CXCR4 at inflamed preatheromas, which occurred at a relatively early phase of atherosclerosis with infiltrated macrophages." (PMID 31004184, 2019). "Type 4 chemokine receptor (CXCR4) plays an important role in immune cell migration during the atherosclerosis progression." (PMID 31004184, 2019). "For example, systemic treatment of atherosclerosis prone mice with the biglycan CXCR4 antagonist AMD3465 resulted in increased atherosclerosis lesion size compared to untreated controls due to increased neutrophil mobilization." (PMID 31191301, 2019). "We demonstrated that MIF is a functional ligand of chemokinereceptors CD74 and CXCR4 and that it participates in the regulation of monocyterecruitment in atherosclerosis promoted by P.gingivalis infection." (PMID 30506423, 2019). "In view of the CXCR4 protein in atherosclerosis, the function and expression of two alternative ligands of CXCR4, MIF and CXCL12 were summarized and compared." (PMID 31004184, 2019). "Various immune cell types participate in plaque growth, most of which demonstrate significant expression of CXCR4, and its regulation was also mediated by multi-factors with contentious perspectives in its functions in atherosclerosis progression." (PMID 28932900, 2018). "Focusing on the role of chemokines in early stages of atherosclerosis development, gene expressions of CXCR4 and ICAM-1 mediators were also analyzed." (PMID 30356351, 2018). "CXCR4 also accumulates progressively during atherosclerosis progression by modulating neutrophil migration, as well as specifically co-localizing with macrophage infiltration." (PMID 28932900, 2018). "Gallium-68 [68Ga]Pentixafor has recently been introduced for the imaging of atherosclerosis by targeting CXCR4." (PMID 28932900, 2018). "In fact, endothelial chemokine receptor CXCR4 activation at low shear stress can play a role in the development of atherosclerosis acting as an important mediator of the endothelial response to damage through interaction with MIF." (PMID 30356351, 2018). "In atherosclerosis, recent cell-specific knockouts of CXCR4 as well as the study of neutrophil-mediated atherogenic effects has established that the CXCR4/CXCL12 axis has cell-dependent protective or exacerbating effects." (PMID 29581527, 2018). "Recently, vascular CXCR4 was identified to limits atherosclerosis by maintaining arterial integrity, and rs2322864, a SNP located within the CXCR4 locus, was detected to be associated with increased risk for CAD." (PMID 29581828, 2018).
atherosclerosis (continued). "Treating endothelium with chemokines suggests that SDF-1/CXCR4 axis plays an important role in the development of atherosclerosis." (PMID 26074989, 2015). "On the basis of all these studies, we strongly assume that SDF-1/CXCR4 biological axis is targeted by astragaloside IV which explains how it intervenes in atherosclerosis." (PMID 26074989, 2015). "The aim of this study was to investigate the effects of AsIV on blood lipids, CD40-CD40L signal system, and SDF-1/CXCR4 biological axis in high-fat diet apoE−/− mice and reveal the molecular mechanisms of AsIV against atherosclerosis." (PMID 26074989, 2015). "During atherosclerosis, CXCR4 plays a protective role by controlling neutrophil mobilization and homeostasis." (PMID 26001902, 2015). "Together, these results show that CXCL12/CXCR4 have interactions with many cells that are relevant in atherosclerosis and is thereby modulating atherosclerosis development." (PMID 26257740, 2015). "In contrast, the role of the CXCL12/CXCR4 axis in native atherosclerosis remains largely unclear, with mostly only in vitro studies shedding some light on the effect of CXCR4 signaling on cell type-specific functions relevant in atherogenesis." (PMID 24966838, 2014). "In a rat model of diabetes, a metabolic disorder associated with a higher prevalence of atherosclerosis, high glucose levels were shown to trigger activation, proliferation, and enhanced chemotaxis of VSMCs via stimulation of the CXCL12/CXCR4 axis." (PMID 24966838, 2014). "Nevertheless, studies dissecting the role of CXCR4 on T- and B-cells in the context of atherosclerosis are scarce." (PMID 24966838, 2014). "The importance of the CXCL12/CXCR4 axis in progenitor cell homing and mobilization will be addressed, as will be the function of CXCR4 in different cell types involved in atherosclerosis." (PMID 24966838, 2014). "In addition to 18F-FDG and 18F-NaF, newer PET tracers are under investigation for better imaging atherosclerosis, such as CXCR4-targeted 68 Ga-pentixafor, CCR2-targeted 64Cu-DOTA-ECL1i, and CCR5-targeted 64Cu-DOTA-DAPTA." (PMID 40289041, 2025). "Additionally, blocking TLR2/CXCR4 can significantly delay or even nearly reverse atherosclerosis induced by Chlamydia pneumoniae infection." (PMID 40535169, 2025). "By exerting atheroprotective effects, CXCR4 modulators may provide a therapeutic option in patients affected with atherosclerosis." (PMID 39776816, 2025). "However, the role of the CXCL12/CXCR4/ACKR3 axis in atherosclerosis includes a large range of cell-type-specific biological effects." (PMID 40986007, 2025). "CXCL12 is thought to promote atherosclerosis progression by signaling downstream of CXCR4." (PMID 39483879, 2024). "Moreover, the SDF-1/CXCR4 interaction inhibits the ABCA1-dependent cholesterol efflux from macrophages to apolipoprotein A1 (ApoA1) thus aggravating the atherosclerosis." (PMID 37894988, 2023). "C-X-C motif chemokine receptor 4 (CXCR4) is a transmembrane chemokine receptor involved in mediating pro-inflammatory leukocytes and is particularly abundantly expressed on monocytes, differentiated macrophages, and T cells in atherosclerosis." (PMID 35888127, 2022). "Our research group could already reveal that arterial CXCR4 is protective against atherosclerosis by maintaining the integrity of the arterial wall." (PMID 35674847, 2022). "Doring et al29 found that CXCR4 could regulate the occurrence and development of atherosclerosis by affecting the function of vascular endothelial cells." (PMID 35607269, 2022). "Additionally, CXCR4 in ECs prevents the development of atherosclerosis by maintaining the function of the endothelial barrier, whereas CXCR4 in SMCs keeps normal phenotype and contractility of the cells." (PMID 36703734, 2022). "However, the mechanism of CXCR4 for systematic cardiovascular and inflammatory activation in patients with atherosclerosis is yet to be elucidated." (PMID 35888127, 2022).